IL15 (interleukin 15)
Diseases named in the same sentence as IL15 in open-access papers (continued):
Sharing a sentence is not in itself a finding about the gene and the disease.
tumor (continued). "In preclinical studies, the administration of IL-15 has antitumor effects in several mouse tumor models." (PMID 32927646, 2020). "IL-15cx or IL-15cx trans-presenting cells show superior bioactivity and antitumor efficacy to IL-15 monomer in multiple preclinical tumor models." (PMID 33628206, 2020). "These approaches are designed to extend the time that IL-15 is present and to potentially augment the anti-tumor response." (PMID 33096755, 2020). "CD8+ T cells in spleen were significantly higher in the IL-15cx treated tumor mice than in control or the IL-15 treated tumor mice." (PMID 33628206, 2020). "An overwhelming number of MDSCs are present in mice with tumors, and the levels of these suppressor cells are still much higher in tumor bearing transgenic mice treated IL-15 or IL-15cx than parent FVB mice." (PMID 33628206, 2020). "IL-15, an autocrine/paracrine cytokine produced by tumor cells, has been shown to promote the proliferation, motility, and invasiveness of CRC cells as well as increase their tolerance and resistance to apoptosis." (PMID 33419310, 2020). "We found that negatively freshly isolated Vδ2+ T cells do not exhibit suppressive behavior, even after stimulation with IL-12/IL-18/IL-15 or the sheer contact with butyrophilin-3A1-expressing tumor cell lines (U251 or SK-Mel-28)." (PMID 31982940, 2020). "In a colitis-associated colon carcinogenesis (CAC) model, IL-15 deficiency suppressed NK and CD8+ T cell immunity, provided a tumor-supporting inflammatory milieu, and increased tumor burden." (PMID 33419310, 2020). "In vivo migration of IL-15 activated NK cells was affected by the tumor as we observed a slight reduction of transferred NK cell homing capacity in the BM and a 2.5-fold enhancement of splenic infiltration in MM-bearing compared to healthy control mice." (PMID 31699153, 2019). "IL-15, either in its soluble form (IL-15sol) or complexed with IL-15Rα (IL-15Rc), has been shown to exhibit potent anti-tumor activities in various experimental cancer studies." (PMID 31856922, 2019). "Th1 cells are known for their anti-tumor capabilities and type 1 ILCs were also shown to have anti-tumor properties in an IL-15 rich environment." (PMID 31024531, 2019). "In WSC group the plasma level of ANGPTL-4 was positively correlated with IL-10 (p=0.04) and IL-15 (p=0.02) in the tumor and with IL-15 (p < 0.01) in the mesenteric adipose tissue." (PMID 31741709, 2019). "Further, the toxicity of IL-15 is less than that of IL-2, but the concentrations of IL-15 required to drive efficient anti-tumor function remain toxic." (PMID 31456796, 2019). "Tumor cell-killing by unprimed CD8 T cells co-cultured overnight with IL-15 DCs was 2–3 fold enhanced against NB4, SH-SY5Y, and U266 cells, i.e., 17.43 ± 14.45% → 43.32 ± 12.32%, 8.46 ± 3.27% → 23.87 ± 6.62%, and 8.82 ± 4.35 → 23.17 ± 10.61%, respectively." (PMID 31336622, 2019). "Related to melanoma, an NDV vector based on the LaSota strain expressing IL-2 and IL-15 efficiently infected tumor cells and demonstrated superior tumor growth suppression compared to the recombinant NDV (rNDV) vector." (PMID 30832256, 2019). "Investigators have engineered IL-15-producing CARs to enhance T cell memory development and incorporate NK cell responses for tumor clearance in vivo." (PMID 30842774, 2019). "Numerous animal tumor models have demonstrated broad anti-tumor activity for various cytokines, including GM-CSF, IL-2, IL-7, IL-12, IL-15, IL-18 and IL-21." (PMID 31856922, 2019). "One is an oncolytic vaccinia virus armed with a superagonist IL-15 (IL-15-IL-15Rα fusion) given alone or in combination with anti-PD-1: combined treatment demonstrated T cell-driven anti-tumor efficacy in in vivo mouse models of cancer." (PMID 30941125, 2019).
tumor (continued). "Ranked third on the cancer immunotherapy trials network (CITN) priority list of immunotherapy agents, the pleiotropic cytokine interleukin (IL)-15 has a lot of potential to boost the anti-tumor immune response and help cure cancer." (PMID 31336622, 2019). "IL-15 is expressed in the tumor microenvironment, required for establishing normal levels of NK cell anti-tumor immune response." (PMID 31552017, 2019). "Recently, IL-15 treated NK cells were shown to maintain anti-tumor activities in the context of an immunosuppressive microenvironment compared with IL-2 treated NK cells." (PMID 31340613, 2019). "Of note, IL-15 suppressed the maturation of miRNA-1245 which is detectable in tumor-derived exosomes in hematopoietic malignancies." (PMID 31803194, 2019). "This compound shows greater biological activity than native IL-15 with increased potency to stimulate NK cell anti-tumor activity." (PMID 31340613, 2019). "Similar to its ability to enhance the anti-tumor effect of NK cells and γδ T cells, IL-15 also enhanced the anti-tumor effect of DNTs against NSCLC both in vitro and in vivo." (PMID 30670085, 2019). "Therapeutic application of exogeneous IL-15 directed to the tumor sites activated and recruited NK cells in mouse models, indicating that IL-15 signaling is essential for NK cell anti-tumor immunity." (PMID 31552017, 2019). "Studies testing membrane-bound (mb) IL-15, tethered to the membrane through a CD8α transmembrane domain, showed enhanced anti-tumor activity when tested in natural killer (NK) cells." (PMID 30863720, 2019). "Recent reports have shown that the administration of IL-15 with its soluble receptor IL-15Rα complex enhanced the bioavailability of IL-15 by about 50-fold and showed elevated tumor-eliminating effects in vivo." (PMID 31827396, 2019). "In a recent study, the activation of the IL-15 signaling in adipose tissue probably activated and expanded the NK cell population and inhibited tumor growth." (PMID 31739287, 2019). "Anti-tumor: ILC1s number expansion exhibits potent cytotoxicity to limit tumor growth in response to IL-15." (PMID 32117199, 2019). "Apolipoprotein A-I, the major component of high-density lipoproteins, binds to its main receptor, SR-BI, which is overexpressed on liver and tumour cells, thereby effectively targeting IL-15 activity within the recombinant protein to the tumour." (PMID 30413827, 2019). "Results showed a further 26.50 ± 22.68% reduction in tumor growth in mice injected with IL-15 plus IL-2-treated DNTs compared to IL-2-treated DNTs." (PMID 30670085, 2019). "This latter strategy relies on the use of ZA and IL-15 to expand terminally-differentiated and anti-tumor CD45ROneg/CD27neg effector memory (TEMRA) Vδ2 cells." (PMID 31849972, 2019). "Transfer of IL-15-stimulated cells reduced substantially (60–70% decrease of CD138+ tumor cell frequency) tumor cell burden in BM as compared to PBS-injected mice, while IL-12/15/18 activated cells were less effective." (PMID 31699153, 2019). "In this strategy, NK cells are modified to produce cytokines such as IL-2 and IL-15 which increase their survival capacity and proliferation and promote anti-tumor activity in vivo." (PMID 30823602, 2019). "Upon transfer of IL-15 activated Cxcr3−/− NK cells, 5T33-bearing mice showed more than 50% reduction of tumor cell frequency in BM compared with mice treated with Cxcr3+/+ IL-15 activated cells or vehicle." (PMID 31699153, 2019). "IL-15 binds to its receptor complex to activate an enhanced anti-tumour response that primarily stimulates the proliferation, activation and cytotoxic functions of natural killer (NK) and CD8 T cells, without stimulating immune-suppressing regulatory T cells." (PMID 31415645, 2019). "NK cells also had anti-tumor responses and were reprogrammed to act on specific cellular pathways when stimulated with different cytokine priming programs, IL-12 and IL-15, or IL-15, or IL-2, in the presence of adenosine." (PMID 31396523, 2019).
tumor (continued). "The flavonoids of Hippophaerhamnoides L (TFH) isolated from berries of sea buckthorn up-regulated the levels of IL-1α, IL-2, IL-7, IL-15 etc. to activate NK cells and its cytotoxicity against tumor cells K562." (PMID 31138762, 2019). "Here, for the first time, we describe the anti-tumor efficacy of subcutaneously administered IL-15 superagonist N-803 (previously known as ALT-803) in combination with an αPD-L1 monoclonal antibody in murine TN breast and colon carcinoma models." (PMID 30898149, 2019). "IL15-NK-EVs displayed longer circulating times, increased tumor-specific delivery, and prolonged intratumoral accumulation (up to 72 hours compared to 48 hours for naive EVs)." (PMID 31754377, 2019). "The adoptive transfer of NK cells from healthy donors showed the killing of stem-like and differentiated tumor cells upon activation with IL-2 and IL-15." (PMID 30841635, 2019). "In agreement, IL-15 mRNA level was inversely correlated with tumor volume in the entire population (three groups together) by linear regression analysis (P = 0.0013)." (PMID 30717773, 2019). "Concerning NK cells and γδ T cells alike, a clear enhancement in tumor cell killing was seen after overnight co-culture with IL-15 DCs against two out of three tumor cell lines tested." (PMID 31336622, 2019). "IL-15 treatment partially overcame this tumor escape mechanism, indicating that different successive treatments are required to restore NK cell response and effectively fight tumor cells." (PMID 31547251, 2019). "An IL-15 superagonist/IL-15Rα fusion complex (ALT-803) rescued NK cytolysis of tumor cell lines from TGF-β1-mediated immunosuppression in vitro and diminished TGF-β1-mediated down-regulation of surface NKG2D." (PMID 31803194, 2019). "CAR T-cells engineered with membrane-bound chimeric IL-15 induce CSC memory T-cells in tumor-specific T-cells in CD19+ leukemia." (PMID 30841635, 2019). "Exposure to IL-2, IL-12, IL-15, or IL-12/15/18 induced a similar “trafficking” signature to that induced by tumor cells: CXCR4 and CD62L expression was downregulated compared to unstimulated NK cells." (PMID 31242243, 2019). "The expression of IL-15 is known to decrease the migration, invasion, and angiogenesis but increase tumor volume by increasing lipid deposition and inflammation in prostate cancer." (PMID 31748686, 2019). "Tumor cell frequency was reduced by 60% after the transfer of IL-15-activated Cxcr3+/+ NK cells while it was reduced by more than 85% after the transfer of the Cxcr3−/− counterpart when compared to PBS-injected mice." (PMID 31699153, 2019). "In WSC, we identified an association between the plasmatic ANGPTL-4, IL-15, and IL-10 in tumor and IL-15 in MES." (PMID 31741709, 2019). "The combination of drug therapy with NK cell stimulating cytokines (IL-2, IL-12, IL-15, and IL-21) or immunomodulatory drugs (IMiDs) can enhance NK cell-mediated tumor killing." (PMID 30823602, 2019). "Both activation protocols promoted degranulation and IFN-γ production by donor NK cells infiltrating the bone marrow of tumor-bearing mice, although IL-15 promoted a faster but more transient acquisition of functional capacities." (PMID 31699153, 2019). "Given that IL-15-associated T cells harbor superior tumor control relative to effector T cells, we measured the impact of E64FC26-treatment on T cell tumor control." (PMID 31779147, 2019). "Anti-CXCR3 mAb treatment in combination with IL-15-activated NK cells and recombinant IL-15 markedly reduced tumor cell burden in the BM while the combination with control IgG had no protective effect." (PMID 31699153, 2019). "IL-2, IL-15 and IL-21 conditioning of total TILs from the resected PanTT26 tumour piece (which includes the TLS) was enriched for CD8+ T cells, as confirmed in the cytotoxicity assay performed with the autologous tumour cell line." (PMID 30377343, 2019).
tumor (continued). "The highest survival was observed in the RT and IL-15 combination group (median 102 days) with 1 of 6 mice showing complete tumor rejection and a development of a long-lasting immunity." (PMID 31179236, 2019). "These so-called IL-15 DCs have already proven themselves superior to the classic IL-4 DCs based on their direct cytolytic activity against tumor cells and their capacity to stimulate adaptive and innate anti-tumor immunity." (PMID 29692776, 2018). "Cytokines enhancing NK-cell proliferation and function such as IL-2 and IL-15 can be used to potentiate NK cell-mediated ADCC against antibody-coated tumor cells, offering the potential for multiple combinatorial immunotherapy strategies against cancer." (PMID 30294328, 2018). "To capitalize on the anti-tumor potential of IL-15, we generated a therapeutic fusion protein (KD033), combining a proprietary high affinity human-PD-L1 antibody (or mouse-PD-L1 surrogate antibody (KD033-surrogate)) with human IL-15." (PMID 30400822, 2018). "We identified an association of TAA-reactive T-cells (defined by IFN-γ production) in correlation with the histopathological grading of the tumor and T-cells cultured with IL-2/IL-15 and IL-21." (PMID 29058035, 2018). "IL-15 boosted degranulation of tumor-infiltrating NK cells to a higher percentage than the basal level seen upon K562 challenge of NK cells from the unaffected distant liver margin." (PMID 29867983, 2018). "The combination of RANTES and IL-15 was shown to improve T-cell trafficking to tumor sites as well as create a favorable environment within the TME to enhance immune cell persistence." (PMID 30386740, 2018). "Pre-exposure of NK cells to recombinant IL-15/IL-15Rα further increased the lysis of olaparib treated tumor cells." (PMID 30486888, 2018). "Clinically, the significant improvement of NK killing of olaparib treated tumor cells can be applied to patients’ endogenous NK cells; but also to patients receiving treatment with IL-15 (N-803) or NK cells for adoptive transfer (haNK cells) as well." (PMID 30486888, 2018). "The fusion with cytokines like IL-21 or IL-15 can activate T and NK cell immunity in the tumor proximity and help tumor clearance." (PMID 30254634, 2018). "The demonstration that IL-15 can recover hepatic NK cell function following tumor exposure supports its inclusion in immunotherapy strategies." (PMID 29867983, 2018). "Stimulation with IL-15 DCs + IPP + tumor cell lines resulted in 13.12 ± 2.68% (for K562 cell line) and 7.35 ± 1.24% (for Daudi cell line) IFN-γ+ γδ T cells." (PMID 29692776, 2018). "Interleukin-15 (IL-15) is a promising candidate for tumor immunotherapy, since it is a strong activator of both CD8+ T and NK cells and in contrast to IL-2 does not activate regulatory T cells." (PMID 30400835, 2018). "In an in vivo vaccination protocol, an IL-15 encoding plasmid linked to TAT CPP and survivin epitope increased the percentage of survivin-specific CD8 T cells with lytic function towards CT26 tumor cells." (PMID 29508006, 2018). "Results show that ADO reprograms NK cells’ anti-tumor responses, and priming NK cells with IL-12 and IL-15 can partially mitigate ADO-induced immunosuppression." (PMID 30400822, 2018). "From the same cases, fresh tumor tissue was cultured in medium containing IL-2, IL-15 and IL-21 to cultivate TILs, and percentage of TCR gamma-delta T-cells (CD3+ TCR γδ+) and NK cells (CD3- CD56+ CD16+) was analyzed by flow cytometry (FC)." (PMID 30400835, 2018). "IL-15 has anti-tumor activity but with limited efficacy due to its unfavorable pharmacokinetic properties and tolerability." (PMID 30400822, 2018). "Fresh tumor from primary (P) and peritoneal metastasis (PM) cancer lesions and colon tissue (C) were cultured in medium containing IL-2, IL-15 and IL-21." (PMID 30400835, 2018). "Using time course mixed culture models, we show that Deep IL-15 enhances the performance of tumor-directed CTLs." (PMID 30400835, 2018).
tumor (continued). "On the other side, expression of IL-15 receptor and autocrine production of IL-15 has been suggested as mechanism of tumor propagation in MM." (PMID 30542346, 2018). "Tumor- reactivity of transduced T cells was determined after expansion in media supplemented with IL-2, IL-7, and IL-15." (PMID 30400835, 2018). "The whole blood of patients with cancer was also exposed to IL-2, IL-15 and IL-21 in culture, which we have previously reported to have a pronounced effect on amplifying tumor-directed T-cell responses." (PMID 29970101, 2018). "Cotransduction of a first generation CD123-targeted CAR to produce dual-switch/IL-15 CD123CAR-NK cells led to rimiducid-dependent control of THP1 tumor outgrowth in vivo beyond 40 days." (PMID 30400835, 2018). "The bicistronic TH/IL-15-based vaccine was the most effective against NB exhibiting tumor remission in 45.5% of mice (5/11 left panel)." (PMID 30452438, 2018). "Pre-activation of NK cells with IL-2 or IL-12, IL-15 and IL-18 results in the generation of NK cells efficient to target and kill tumor cells." (PMID 30323819, 2018). "The immune response induced by TH-directed vaccination was further enhanced by the co-expression of IL-15 resulting in protection of mice from tumor growth and prevention of spontaneous metastasis after a lethal challenge with NB." (PMID 30452438, 2018). "Instead, effective cytotoxicity against tumor cells requires co-engagement of specific activating receptors or pre-activation by cytokines (e.g., IL-2 or IL-15)." (PMID 30250471, 2018). "The localized expression of IL-15 by VSV in the tumor microenvironment induced anti-tumor CD8 T-cell responses in a murine model of colon carcinoma with enhanced survival of treated mice as compared to the control group." (PMID 29473868, 2018). "Inducible MyD88/CD40 is an activation switch that supports NK cell expansion, persistence and anti-tumor activity in vitro and in vivo when paired with autocrine IL-15 expression." (PMID 30400835, 2018). "Interleukin 15 (IL-15) regulates the development, survival, and functions of multiple innate and adaptive immune cells and plays a dual role in promoting both tumor cell growth and antitumor immunity." (PMID 29255466, 2017). "In this experiment, the cytokine response analyses showed significant up-regulation of IL-12, IL-2, IL-15 and IL-18 in the progressors, which reflects an anti-tumor immunity in the rapidly growing tumors." (PMID 28381295, 2017). "Concurrent trastuzumab and IL-15 administration triggered an immune response in BT474- and even in SK-BR-3-based HTM that resulted in tumor eradication and caused reduced metastasis in the lung." (PMID 27835865, 2017). "An increase in mRNA levels of IL-2, IL-12p40, IL-12p70, and IL-15 correlated with their increased protein levels in splenocytes of bortezomib-treated tumor-bearing mice compared with untreated tumor-bearing mice." (PMID 28052005, 2017). "Although pulse zoledronate stimulation with IL-15 preserved early memory subsets, adoptive immunotherapy with IL-15-derived Vγ2Vδ2 cells equally inhibited PC-3 tumor growth as those derived with IL-2." (PMID 28239463, 2017). "In this respect, a recent study investigating the relative effect of IL-2 and IL-15 in in vitro treatment described a better persistence of IL-15 effects on NK cells anti-tumor functions upon cytokine withdrawal." (PMID 28956813, 2017). "In this report, an oncolytic Ad (Ad5Δ24) was armed with chemokine genes CCL5 and IL-15 and applied as a recruiter (via CCL5) and sustainer (via IL-15) of CAR-T cells (reactive against the tumor-associated ganglioside GD2) into/within the TME." (PMID 28555136, 2017). "It was implied to be associated with apoptosis of GBM cells and to participate in IL-15 induced activation of tumor-specific gamma delta T cells, a subset of T cells that express a unique T cell receptor and are multi-functional in cancer." (PMID 28241741, 2017).